DES (desmin)
Diseases named in the same sentence as DES in open-access papers (continued):
Sharing a sentence is not in itself a finding about the gene and the disease.
cavernous hemangioma (1 paper, 2013). A hemangioma characterized by the presence of cavernous vascular spaces. "A focal positive reaction with actin and desmin was detected at the walls of the cavernous hemangioma-like vascular structures." (PMID 24187557, 2013). "A focal positive reaction was present with actin and desmin at the walls of the cavernous hemangioma-like vascular structures." (PMID 24187557, 2013). "Mature endothelial cells in cavernous hemangioma give a positive reaction with Factor VIIIra, and pericytic cells give a positive reaction with actin/desmin." (PMID 24187557, 2013).
chorea-acanthocytosis (1 paper, 2023). Chorea-acanthocytosis (ChAc) is a form of neuroacanthocytosis and is characterized clinically by a Huntington disease-like phenotype with progressive neurological symptoms including movement disorders, psychiatric manifestations and cognitive disturbances. "In this study, we reported disordered microtubular cytoskeleton, and cytokeratins and desmin in fibroblasts extracted from patients with chorea-acanthocytosis (ChAc), when evaluated against fibroblasts from that of non-diseased donors." (PMID 37744224, 2023).
Cirrhosis (1 paper, 2013). A chronic disorder of the liver in which liver tissue becomes scarred and is partially replaced by regenerative nodules and fibrotic tissue resulting in loss of liver function. "Morphological polymorphism was most expressed in α-SMA and desmin positive cells that are located in connective tissue stripes of livers with cirrhosis." (PMID 23497565, 2013). "Vascular smooth muscle cells and individual cells situated in connective tissue stripes were also strongly positive to α-SMA and desmin in livers with cirrhosis." (PMID 23497565, 2013). "In the livers with cirrhosis, immunopositivity to α-SMA and desmin was observed in cells in portal and septal spaces, at the edge between fibrotic septa and the surrounding parenchyma and in perisinusoidal spaces." (PMID 23497565, 2013). "In the livers with cirrhosis, immunopositivity to α-SMA and desmin was observed on cells in portal and septal spaces, at the edge beetween fibrotic septa and the surrounding parenchyma and in perisinusoidal spaces." (PMID 23497565, 2013). "Progressive fibrillogenesis in fallow deer livers with parasite cirrhosis is most probably a consequence of the stepped up expression of α-SMA and desmin on portal, septal, interface, and perisinusoidal MFs." (PMID 23497565, 2013).
colitis (1 paper, 2023). Inflammation of the colon. "For instance, we detected high levels of IgG anti cardiac myosin before ICI exposure in a patient who subsequently experienced immune related myocarditis and very high pre-ICI levels of IgG anti-desmin in a patient who experienced colitis." (PMID 37865776, 2023).
colon adenocarcinoma (1 paper, 2014). "As normal resident intestinal myofibroblasts are not immunoreactive to the DMTX1/1E8.33 mAb, these procollagen 11A1+ desmin- colon adenocarcinoma stromal cells could be a type of “activated myofibroblasts”." (PMID 25417197, 2014). "Although not formally proven, procollagen 11A1+ colon adenocarcinoma stromal cells, being spindle-shaped, seem to simultaneously express alpha smooth muscle actin and vimentin, but no desmin; these traits confer to them a myofibroblast-like phenotype rather than a pericyte one." (PMID 25417197, 2014).
congenital cataracts (1 paper, 2021). "A missense mutation of the arginine 120 to glycine (R120G) in αB-crystallin causes a desmin-related myopathy and congenital cataracts, because this mutation alters protein–protein interaction, with an increase in its cytoplasmic aggregation." (PMID 34203836, 2021).
COVID-19 (1 paper, 2025). A disease caused by infection with severe acute respiratory syndrome coronavirus 2. "The results of these genetic factors in the genes (TLR7, UNC13D, DES, SPEG, LZTFL1, ABO, ILRUN, and CACFD1) provide substantial insights into the genesis of cardiovascular issues linked with COVID-19." (PMID 40002898, 2025). "Mutations in genes such as the heterozygous desmin gene (DES) and Striated Muscle Enriched Protein Kinase (SPEG), associated with cardiovascular disorders, have been recognized as possible risk factors for COVID-19 mortality." (PMID 40002898, 2025).
cyst (1 paper, 2021). A sac-like closed membranous structure that may be empty or contain fluid or amorphous material. "In the lung tissues of patients with LAM, we investigated the expression levels of HMB45, desmin and changes in cyst formation." (PMID 34445268, 2021).
dermatofibrosarcoma protuberans (1 paper, 2025). Dermatofibrosarcoma protuberans (DFSP) is a rare infiltrating soft tissue sarcoma, generally of low grade malignancy, arising from the dermis of the skin and characteristically associated with a specific chromosomal translocation t(17;22). "Stains were negative for AE1/3, HHV-8, DOG1, CD34, S100, CD56, SMA, and Desmin, consistent with a fibrohistiocytic origin and most suggestive of dermatofibrosarcoma protuberans (DFSP)." (PMID 41200607, 2025).
distal hereditary motor neuropathy (1 paper, 2020). "Several mutations in sHSPs have been described that are associated with pathologies, such as distal hereditary motor neuropathy (dHMN), Charcot-Marie-Tooth (CTM) disease, and desmin-related myopathy." (PMID 32253739, 2020).
dystrophin deficiency (1 paper, 2025). "This genetic approach allowed us to investigate the impact of partial desmin reduction in the context of dystrophin deficiency." (PMID 41163301, 2025). "It is possible that, in the particular context of dystrophin deficiency, presently unknown phosphorylated sites on desmin have positive effects on filament assembly and/or stability, an interesting hypothesis to be addressed in future detailed studies." (PMID 41163301, 2025).
end-stage renal disease (1 paper, 2025). "Rhein restored nephrin/podocin and suppressed desmin, thereby protecting podocytes, which are critical for preventing progression to end-stage renal disease (ESRD), in ~30% of ORG patients." (PMID 41586196, 2025).
endothelial dysfunction (1 paper, 2012). In vascular diseases, endothelial dysfunction is a systemic pathological state of the endothelium (the inner lining of blood vessels) and can be broadly defined as an imbalance between vasodilating and vasoconstricting substances produced by (or acting on) the endothelium. "Interestingly, mice subjected to the AFD regimen displayed downregulated expression levels of the endothelial dysfunction marker endothelin-1, the inflammatory markers MCP-1 and CD68 and the fibrosis markers desmin when compared to HFD fed mice." (PMID 23049881, 2012).
esophageal tumors (1 paper, 2025). "Markers such as CK, P40, and P16 effectively excluded common epithelial cell-derived esophageal tumors, while negative staining for SMA, desmin, and MDM2 further supported the differential diagnosis." (PMID 40636370, 2025).
fibroepithelial tumours (1 paper, 2008). "Tse described the immunohistochemical profile of the infrequent MSGCs in phyllodes tumours, commenting that both the MSGCs and stromal cells expressed vimentin strongly but not desmin; and in some but not all fibroepithelial tumours, both MSGCs and stromal cells expressed actin weakly." (PMID 18673528, 2008).
focal glomerulosclerosis (1 paper, 2023). "Oral nicotine delivery in rats with proteinuria-induced renal inflammation showed dose-dependent reduces proteinuria, glomerular desmin deposition, decreased glomerular podocin, decreased focal glomerulosclerosis (FGS) score, and reduced infiltration of macrophages and myofibroblasts." (PMID 37264452, 2023).
gastric adenocarcinoma (1 paper, 2025). "On immunohistochemistry, the absence of epithelial markers (CK7, CK20) along with strong positivity for smooth muscle markers (Desmin, SMA) can reliably rule out gastric adenocarcinoma." (PMID 40896433, 2025).
gastric leiomyoma (1 paper, 2021). A rare benign smooth muscle neoplasm arising from the wall of the stomach. "Moreover, gastric leiomyoma was immunoreactive for desmin, actin, calponin, and h-caldesmon." (PMID 34516510, 2021).
gastric tumours (1 paper, 2008). "In particular, in gastric tumours, CD34, Desmin and Smooth Muscle Actin (SMA) were positive in 98%, 9% and 41% of the samples respectively; while in extra-gastric tumours, they were positive in 65%, 0% and 56% of the samples." (PMID 18474118, 2008).
giant cell tumor (1 paper, 2025). A benign, intermediate, or malignant tumor that arises from the bone or soft tissue. "The expression of desmin and SMA is also seen in other tumors, such as myofibroblastic tumors, osteoblastic fibromucinous tumors, and giant cell tumors of the tendon sheath, which further complicates the interpretation of these markers in ASPS." (PMID 40176092, 2025).
glaucoma (1 paper, 2024). Increased pressure in the eyeball due to obstruction of the outflow of aqueous humor. "The authors of the study were able to detect the expression of TUBB3 in desmin-, PDGFR-β- and α-SMA-positive pericytes, as well as in endothelin-1-positive endothelial cells in eyes affected by glaucoma." (PMID 39318470, 2024).
Granuloma (1 paper, 2024). A compact, organized collection of mature mononuclear phagocytes, which may be but is not necessarily accompanied by accessory features such as necrosis. "In order to obtain a model-independent proof of the results from mouse and human cell lines, desmin+ cells were visualized in granuloma of a histologic slice of a liver biopsy that was routinely taken for diagnosis from a 31-year-old male patient suffering from schistosomiasis." (PMID 39404406, 2024).
hemochromatosis (1 paper, 2022). A disorder of iron metabolism characterized by a triad of HEMOSIDEROSIS; LIVER CIRRHOSIS; and DIABETES MELLITUS. "Mutations in desmin (DES) and hemochromatosis gene (HFE1) were identified." (PMID 35456383, 2022).
histiocytic sarcoma (1 paper, 2022). An aggressive malignant neoplasm with a poor response to therapy, usually presenting as stage III/IV disease. "In Mongolian gerbils, there were two cases of abdominal scent gland epithelioma (both two-year-old males) and one case of histiocytic sarcoma located in the nasal area (age unknown, female; tumour cells expressed Iba-1 and vimentin, clone V9, and were negative for desmin and α-SMA-)." (PMID 35454212, 2022).
Histiocytosis (1 paper, 2017). An excessive number of histiocytes (tissue macrophages). "Therefore, the first attempt to characterize the skin biopsy fragments was made, a diagnosis of Lanherhans Cells Histiocytosis was discussed, based on CD68+++, CD 45+, MPO+, CD1a-, S-100-, desmin -, MY14-." (PMID 29450403, 2017).
hydrocele (1 paper, 2024). "The sacs in inguinal hernia and hydrocele contain smooth muscle cells distributed in bundles which express desmin and SMA." (PMID 38816716, 2024). "Inguinal hernia and hydrocele sacs contain more smooth muscle cells and myofibroblasts and express desmin and SMA in greater magnitude than the sacs from UDT." (PMID 38816716, 2024). "Our study showed positive staining for desmin and SMA in 68%, 86% and 20% of the processus vaginalis sac of inguinal hernia, hydrocele and UDT, respectively and this difference was statistically significant." (PMID 38816716, 2024). "Overall, positive staining for desmin and SMA was observed in 25 (68%), 18 (86%) and 4 (20%) specimens of inguinal hernia, hydrocele and UDT respectively; p<0.001." (PMID 38816716, 2024).
Hyperglycemia (1 paper, 2023). An increased concentration of glucose in the blood. "We found that desmin was expressed in a diffuse pattern following hyperglycemia and was undetectable in intercalary disks, in contrast to some specimens from the NT group." (PMID 36983924, 2023). "The current study evaluated changes in embryonic heart development and the expression levels of sarcomeric proteins (troponin I, desmin, and TNNI3K), junctional proteins, glucose transporter-1, and Ki-67 under fetal hyperglycemia." (PMID 36983924, 2023).
hyperthyroidism (1 paper, 2025). Overactivity of the thyroid gland resulting in overproduction of thyroid hormone and increased metabolic rate. "Our findings revealed that, despite median left ventricular dimensions not being significantly different from ones observed in healthy animals, cats with hyperthyroidism exhibited similar alterations in desmin and interleukin-10 expression to those seen in HCM-affected cats." (PMID 40564271, 2025).
Hypoxemia (1 paper, 2025). An abnormally low level of blood oxygen. "Hypoxemia may suppress uric acid excretion by affecting desmin protein levels in podocytes and Na+-K+-ATPase activity." (PMID 39937787, 2025).
Inguinal hernia (1 paper, 2024). Protrusion of the contents of the abdominal cavity through the inguinal canal. "However, one specimen of inguinal hernia showed desmin positive and vimentin positive myofibroblasts and another specimen of inguinal hernia showed desmin positive and smooth muscle actin positive myofibroblast." (PMID 38816716, 2024). "Two processus vaginalis sacs of inguinal hernia showed few scattered smooth muscles which were negative for both desmin and smooth muscle actin (SMA)." (PMID 38816716, 2024). "One specimen of inguinal hernia was positive for desmin but negative for SMA and another specimen of inguinal hernia was positive for SMA but negative for desmin." (PMID 38816716, 2024).
injury (1 paper, 2023). Damage inflicted on the body as the direct or indirect result of an external force, with or without disruption of structural continuity. "So, we wanted to know whether there were differences in migration, activation and proliferation between mGFP+ and Desmin+ HSCs in CCl4‐induced liver injury." (PMID 37246473, 2023).
intimal sarcoma (1 paper, 2019). A malignant neoplasm arising from the large blood vessels. "Vimentin is frequently positive in intimal sarcoma, whereas vascular markers such as CD31, CD34, vWF, and smooth muscle cell markers such as desmin are usually negative." (PMID 30925179, 2019).
invasive breast carcinoma (1 paper, 2018). A carcinoma that infiltrates the breast parenchyma. "In addition, hATT-CMs were also enriched in complement component 3 (C3) (20-fold change), involved in the activation of the complement system, and in vimentin and desmin (8.5-fold and 6.5 fold change), which are mesenchymal cell proteins related to an invasive breast cancer phenotype." (PMID 30123423, 2018).
Kaposi's sarcoma (1 paper, 2021). A malignant neoplasm characterized by a vascular proliferation which usually contains blunt endothelial cells. "The tumor was positive for cluster of differentiation 31 (CD31), CD34, and HHV-8 immunostains and negative for smooth muscle antibody (SMA) and desmin immunostains, consistent with Kaposi sarcoma." (PMID 33754107, 2021).
left ventricular hypertrophy (1 paper, 2016). Enlargement of the LEFT VENTRICLE of the heart. "Using two-dimensional electrophoresis (2-DE) and mass spectrometry, it was found that, at 48 weeks, when left ventricular hypertrophy is established, desmin protein levels are up-regulated." (PMID 27512079, 2016).
leiomyomatosis (1 paper, 2021). A condition characterized by the presence of numerous small benign smooth muscle neoplasms located throughout the body. "In the report, the immunostaining of the leiomyomatosis-like LAM lesion showed positivity for desmin, caldesmon, HMB-45, and CD117, and showed negativity for CD34." (PMID 34918628, 2021).
lymphangioleiomyomatosis (1 paper, 2026). A multifocal neoplasm with perivascular epithelioid cell differentiation affecting almost exclusively females of child-bearing age. "However, immunohistochemical stains demonstrated tumor positivity for HMB45, desmin, and Cathepsin K, and genetic testing revealed a TSC1 variant, leading to a definite diagnosis of uterine PEComa with lymphangioleiomyomatosis (LAM)-like features." (PMID 41755808, 2026).
malocclusion (1 paper, 2014). "Furthermore, none of the wild-type, desmin−/− or mdx4cv mice developed malocclusion during the course of this study." (PMID 24922526, 2014).
mucosal melanoma (1 paper, 2023). A melanoma that arises from a mucosal site. "Furthermore, some mucosal melanomas can also stain for desmin." (PMID 37041531, 2023).
myotonic dystrophy type 1 (1 paper, 2017). Steinert disease, also known as myotonic dystrophy type 1, is a muscle disease characterized by myotonia and by multiorgan damage that combines various degrees of muscle weakness, arrhythmia and/or cardiac conduction disorders, cataract, endocrine damage, sleep disorders and baldness. "An ARVC-like phenotype was described in desmin-related myopathy and myotonic dystrophy type 1." (PMID 28750076, 2017).
nephritis (1 paper, 2020). Inflammation of renal tissue. "Indeed, the podocyte injuries caused by the induction of anti-Thy 1.1 nephritis were evaluated in the present study not only by the amount of albuminuria/proteinuria, but also by the expression of WT-1, podocin, and desmin." (PMID 32478392, 2020).
Neural tumors (1 paper, 2017). "Neural tumors usually stain positively for S-100 protein and neuron-specific enolase but not for desmin and smooth muscle actin." (PMID 29238412, 2017).
neurogenic muscle atrophy (1 paper, 2022). "A direct role for calpain-1 has been demonstrated for desmin filament disassembling in neurogenic muscle atrophy, since calpain-1 down-regulation prevents desmin loss, myofibril destruction and muscle atrophy." (PMID 36422289, 2022).
obstructive sleep apnea (1 paper, 2024). "Our earlier findings of disorganization and accumulation of aggregates of desmin in soft palate muscles of obstructive sleep apnea (OSA) patients indicate muscle injury and the occurrence of pre- and post-translational modifications in the protein synthesis." (PMID 38566246, 2024). "However, we earlier reported that a subgroup of muscle fibers in the soft palate of healthy subjects and obstructive sleep apnea patients (OSA) lacked immunoexpression for desmin." (PMID 38566246, 2024).
oral squamous cell carcinomas (1 paper, 2019). "Previous laser capture microdissection studies in both CRC and oral squamous cell carcinomas show that tumor buds over-express EMT-related genes such as ZEB1, ZEB2, DES, TGFB3, and VIM in comparison to the main tumor mass." (PMID 31316988, 2019).
oropharyngeal cancer (1 paper, 2018). Carcinoma, predominantly squamous cell, arising from the epithelial cells of the oropharynx. "For CDCD3 (Desmin), only one cancer related publication could be retrieved that reported a MS4D7/CDCD3 translocation with unknown function in oropharyngeal cancer." (PMID 30618566, 2018).
pancreatic ductal adenocarcinoma (1 paper, 2014). An infiltrating adenocarcinoma that arises from the epithelial cells of the pancreas. "We have very recently reported that procollagen 11A1+ cancer-associated stromal cells of pancreatic ductal adenocarcinoma co-express αSMA, and/or vimentin, and/or desmin in different proportions." (PMID 25417197, 2014).
Pancytopenia (1 paper, 2020). An abnormal reduction in numbers of all blood cell types (red blood cells, white blood cells, and platelets). "A 7-year-old boy presenting with severe pancytopenia was diagnosed with metastatic RMS after bilateral bone marrow aspiration and biopsy (BMAB) revealed infiltration with alveolar-pattern RMS cells, which were immunoreactive to desmin and myogenin." (PMID 32669548, 2020).
prostate tumors (1 paper, 2018). "Remarkably, the top three most variable proteins in BPH are the three proteins known or used in the diagnosis of prostate tumors, including PSA/KLK3, prostatic acid phosphatase (PAP)/acid phosphatase, prostate (ACPP), and Desmin (DES)." (PMID 30090875, 2018).
prostatic leiomyoma (1 paper, 2013). "In contrast with prostatic leiomyoma with atypia, these cells are intensely immunoreactive for vimentin instead of desmin and actin." (PMID 23781384, 2013).